TNF (tumor necrosis factor)
Diseases named in the same sentence as TNF in open-access papers (continued):
Sharing a sentence is not in itself a finding about the gene and the disease.
Sepsis (continued). "Early-stage acute inflammation in sepsis is primarily mediated by neutrophils, while multiple inflammatory factors, such as tumor necrosis factor and various interleukins, may activate the coagulation cascade, leading to micro-thrombosis." (PMID 38807426, 2024). "Serum levels of TNF-α and IL-6 vary highly between newborns during sepsis." (PMID 38562936, 2024). "In most of the pre-clinical studies, anti-TNF-α drugs are administered around the onset of sepsis." (PMID 38294676, 2024). "The sepsis-induced renal damage led to an increase in TNF, TNF receptor, and IL-6 levels." (PMID 36937479, 2023). "In a sepsis model characterized by significant systemic inflammation, sleep in rats exhibited a fragmented pattern, which was found to be influenced by elevated mRNA and protein levels of cytokines, including IL-1β, IL-6, and TNF-α, in the nervous system." (PMID 37872570, 2023). "It was found that supplementation with omega-9, or oleic acid, is crucial in the metabolic dysfunction that occurs during sepsis because it increases the levels of the anti-inflammatory cytokine IL-10, lowers levels of the pro-inflammatory cytokines TNF- and IL-1, and inhibits neutrophil migration." (PMID 37764396, 2023). "In vivo, RDN could evidently decrease the expression levels of apoptosis-related proteins, alleviate mitochondrial damage, reduce lung tissue edema, down-regulate the level of TNF-α in the serum, and improve the mortality of sepsis in mice." (PMID 37465664, 2023). "TNF is another well-studied inflammatory cytokine but has not previously been associated extensively with the prediction or prognosis of sepsis." (PMID 37691028, 2023). "During sepsis, the abundant presence of PRRs in the circulation activates PAMPs, which initiate a downstream cascade resulting in the release of pro-inflammatory mediators, including IL-1, IL-6, and TNF-α." (PMID 37510681, 2023). "To explore whether SLAMF7 regulate the production of proinflammatory cytokines induced by sepsis in vivo, we determined the concentrations of TNF-α, IL-1β, and IL-6 in serum and supernatants of liver, lung, and PL." (PMID 36749634, 2023). "TNF‐α and IL‐6 are the first cytokines activated and released during the acute infectious period, initiate the SIRS response to sepsis, and are key to the deterioration of patients with septic shock, while PCT is a diagnostic and prognostic marker of sepsis." (PMID 37102655, 2023). "Although a few studies describe standardized protocols for measuring LPS-induced TNF-α production for sepsis, scalable analytic validity may remain challenging." (PMID 36825018, 2023). "The sustained production of IFN-γ and TNF-α can lead to macrophage activation syndrome associated with hemophagocytic lymphohistiocytosis (HLH), which contributes to the anaemia that is characteristic of sepsis and almost all systemic infections." (PMID 37686271, 2023). "In addition, it has been also reported that XBJ effectively reduced circulating IL-1β, IL-6, and TNF-α in CLP rats within 12 h after sepsis." (PMID 37219401, 2023). "In our study, TNF-α is a core target of anti-inflammation in SIC, and NG-R1 may regulate the inflammatory response during myocardial injury in sepsis by mediating TNF-α expression, thereby alleviating cardiac injury and cardiac dysfunction." (PMID 36713827, 2023). "We found that the A allele of the rs1800629 polymorphism of TNF-α was positively correlated with sepsis in our patient population, with the results not being affected by the ARDS or CURB-65 scores." (PMID 37630611, 2023). "Moreover, KEGG pathway analysis indicated that NF-κB signaling pathway, AGE-RAGE signaling pathway, cGMP-PKG signaling pathway, staphylococcus aureus infection, TNF signaling pathway were involved in the process of CRRT-mediated sepsis recovery." (PMID 36650427, 2023). "However, attempts to improve sepsis therapeutic outcomes by targeting proinflammatory mediators, such as TNF and IL1 antagonists and TLR blockers, have been unsuccessful." (PMID 37255592, 2023).
Sepsis (continued). "Anti-PD-L1 antibodies have shown significant improvement in liver injury morphology in CLP mice by reducing glutamic pyruvic transaminase (ALT) and glutamic oxaloacetic transaminase (AST) release, as well as decreasing TNF-α, interleukin (IL)-6, and IL-10 mRNA levels in the liver after sepsis." (PMID 38193090, 2023). "Sepsis-induced multiple organ injuries are accompanied by an excessive response of innate inflammation, which stimulates the secretion of multiple inflammatory cytokines, such as TNF-α and IL-6." (PMID 37251537, 2023). "Indeed, pro-inflammatory cytokines, including IL-6 and TNF-α, are able to activate the coagulation cascade and to downregulate anticoagulant system in sepsis." (PMID 37569751, 2023). "One study demonstrated that TNF-α levels were elevated 24 hours after sepsis induction in mice." (PMID 36937479, 2023). "M1-type macrophages are typically characterized by high levels of oxidative metabolites (reactive oxygen species and NO) and pro-inflammatory cytokines (tumor necrosis factor alpha [TNF-α] and interleukin [IL]-6), which amplify the inflammatory cytokine storm and aggravate sepsis." (PMID 38066526, 2023). "Furthermore, administering AM and AMBP-1 following sepsis induction in rats reduced inflammatory indices including circulating TNF-α, IL-6, and IL-1β." (PMID 37113606, 2023). "In a recent report, in mice with LPS-induced sepsis, G-Rg6 suppressed TNF-α, IL-6, and IL-1β and increased IL-10, thereby inducing the expression of miR-146a and acting as an anti-inflammatory agent in bone marrow-derived macrophages, which are known to regulate inflammatory responses." (PMID 38202632, 2023). "Moreover, the ratio of IL10/TNF, a reported indicator of sepsis-induced immunosuppression and sepsis-related mortality, was significantly correlated with the IRG risk score." (PMID 37033939, 2023). "The concentration of TNF-γ in peripheral blood were highest in sepsis group and IL-7 antibody treatment could decrease the concentration of TNF-α." (PMID 37113759, 2023). "Furthermore, the nuclear translocation of NF-κB activates the transcription of several inflammatory cytokines, including TNF-α and IL-6, and eventually triggers cytokine storms during sepsis." (PMID 38343439, 2023). "In addition, NRF2-mediated transcription of antioxidant enzymes reduces ROS levels and suppresses neutrophil production of IL-6 and TNF-α in sepsis models." (PMID 36671034, 2023). "Exosomes derived from adipose stem cells could reduce the expression of IL-1β, TNF-α and IL-6 in macrophages during sepsis while also downregulating M1 markers (iNOS and CD86) expression." (PMID 37635258, 2023). "Additionally, the plasma levels of IL-1Ra, IL-17A, CCL19, CX3CL1, and TNF were significantly higher in septic patients compared to the non-sepsis group." (PMID 37691028, 2023). "Moreover, in a rat sepsis model, the injection of ApoMSCs improved survival and reduced the levels of plasma TNF-α and circulating Th1 cells." (PMID 37185486, 2023). "The involvement of TNF-a and IL-1 in sepsis has been extensively documented in various studies, encompassing both animal models of septic shock and investigations conducted on human subjects afflicted with sepsis." (PMID 38275661, 2023). "verified that the miR-125-mediation MCEMP1 suppression could decrease the sera levels of TNF-α, IL-1β, and IL-6, and the programmed cell death facilitated the T leukomonocyte activity, hence attenuating the immune activity of sepsis mice." (PMID 37359526, 2023). "The excessive proinflammatory response could result in an overproduction of TNF-α, which while negatively correlated with bacterial load, produced sepsis-like condition and systemic host damage." (PMID 40809472, 2023). "Tumor necrosis factor-α (TNF-α)-induced necroptosis contributes to the pathophysiology of sepsis, so inhibiting necroptosis might be expected to improve clinical outcomes in septic patients." (PMID 36765040, 2023).
Sepsis (continued). "Its production increases in patients with septicemia and infections caused by gram-negative bacteria due to inflammatory cytokines, such as tumor necrosis factor-alpha and interleukin-6 (IL-6)." (PMID 37664550, 2023). "It was observed that supplementation of all three Grecian honeys to sepsis-induced mice significantly reduced TNFα-serum levels, as well as significantly reducing the expression of TNFα and iNOS from harvested liver tissue comparable to that of the manuka honey." (PMID 37631069, 2023). "When sepsis begins, upregulation and activation of HATs open chromatin structure and promote transcription of a large number of pro-inflammatory genes, including TNFα, IL-1β, and iNOs." (PMID 36774341, 2023). "During sepsis, Kupffer cells, macrophages, and other immune cells are activated, producing numerous inflammatory mediators, including interferons, interleukin-6, interleukin-1β, interleukin-8, and tumor necrosis factor." (PMID 37575984, 2023). "TNFα is involved in the pathogenesis of cardiovascular diseases, such as acute myocardial infarction, chronic heart failure (HF), atherosclerosis, viral myocarditis, cardiac allograft rejection, and sepsis-induced cardiomyopathy." (PMID 36902036, 2023). "However, RAT prevented sepsis‐induced overexpression of cortical tissue tumor necrosis factor alpha (TNF‐α; 51 ± 16% decrease; p = 0.003) and medullary Thr‐495 phosphorylation of endothelial nitric oxide synthase (eNOS; 63 ± 18% decrease; p = 0.015)." (PMID 37548350, 2023). "In sepsis-induced cholestasis, TNFα was the driving force to alter BA metabolism." (PMID 37280200, 2023). "During sepsis, an impact of the complement activation product C5a on podocytes has been proposed, whereby it induces the secretion of pro-inflammatory cytokines like IL-6 and TNF, which can magnify tissue damage and increase ROS production." (PMID 37542608, 2023). "Due to its important role in murine sepsis, TNF is put forth by some as the key cytokine in sepsis." (PMID 37869001, 2023). "Besides, Ureaplasma infection increased the infiltration of inflammatory cells, releasing cytokines of interleukin 6 (IL-6), matrix metalloproteinase 8 (MMP8), tumour necrosis factor α (TNFα) and contributing to late-onset sepsis (LOS)." (PMID 37365524, 2023). "Our data confirm that glutamine at 10 mM before or after stimulation cannot modulate any induction effect of either LPS or HS on relative HSP90α gene expression, monocyte HSP90α protein, and supernatant IL-1β, IL-6, IL-8, IL-10, and TNF-α concentrations of PBMCs in sepsis." (PMID 36615909, 2023). "High concordance between LPS-induced TNF concentrations at 4 h and 18 h suggests that 4 h of LPS stimulation may be adequate for assessing immune paralysis in sepsis." (PMID 37831231, 2023). "Release of ROS may trigger EGCX degradation when exposed to generation of TNF‐α and endotoxin, as well as inflammatory states, including sepsis." (PMID 37904703, 2023). "While immune paralysis has historically been defined as the impaired ability to produce TNF in response to endotoxin exposure, increasing awareness of the severity of lymphocyte apoptosis and adaptive immune dysfunction in sepsis has created a need to concurrently interrogate lymphocyte function." (PMID 37831231, 2023). "Inflammatory cytokines are linked to the progression of sepsis by causing an excessive inflammatory response, and HMGB1 functions as a proinflammatory molecule to increase the secretion of inflammatory cytokines such as TNF-α, IL-6 and IL-1β." (PMID 38026444, 2023). "According to a clinical study involving 81 patients with severe pneumonia complicated with sepsis, the expression levels of TNF-α, IL-6, IL-8, and other inflammatory factors in the group that received Tα1 under the basal epithelium were significantly reduced compared with those in the control group." (PMID 36816800, 2023).
Sepsis (continued). "In addition, increasing levels of inflammatory cytokines such as interleukin (IL)-6 and tumor necrosis factor-alpha (TNF-α) trigger the inflammatory immune response and predispose patients with cirrhosis to infectious complications such as sepsis." (PMID 36983211, 2023). "Sepsis represents a systemic response where LPS interacts with host cell receptors, generating numerous pro-inflammatory cytokines: tumor necrosis factor-alpha (TNF-α), interleukin (IL)-1β, IL-6, IL-12, and inflammatory mediators (nitric oxide (NO))." (PMID 38203627, 2023). "Research on TNF-α and septicaemia suggests that the synthesis of large amounts of proinflammatory cytokines during SIRS is rather harmful for the body, whereas blocking the cytokines could prevent the development of generalised infection." (PMID 37686271, 2023). "The present study demonstrated that NG-R1 could protect against SIC and by regulating the expression of TNF-α inflammatory factors, providing a new idea for sepsis drug development." (PMID 36713827, 2023). "In the early stage of sepsis, the host reacts to extracellular bacteria, parasites, fungi, or viruses by producing proinflammatory cytokines such as interleukin-6, interleukin-1, and tumor necrosis factor-alpha (TNF-α)." (PMID 36980658, 2023). "The high concentrations of PCT and TNF-a can be used as valuable predictors of sepsis." (PMID 37296721, 2023). "Specimen collections occurred after 24 h of severe sepsis giving time for ferritin levels to reach their peak; however, cytokines expected to peak in the first 6 h of sepsis such as IL-1β and TNF may have been higher if sampled earlier." (PMID 37674218, 2023). "The typical pro-inflammatory cytokine panel of sepsis includes TNF-α, IL-1β, IL-12, and IL-18." (PMID 37569751, 2023). "Nevertheless, some studies suggested that subgroups of sepsis patients with excessive inflammation may benefit from immunosuppressive therapy, such as IL-1 receptor blockade or anti-TNF neutralizing antibody." (PMID 37144032, 2023). "Attenuation of sepsis and TNF-induced miR-193b-5p upregulation." (PMID 36834784, 2023). "In the same study, in vitro exposure of mesangial cells to NO and inflammatory mediators (IL1β and TNF) synergistically downregulated the angiotensin II type 1 receptor I, which in principle could induce hypotensive reactions during sepsis." (PMID 37542608, 2023). "Additionally, while TNFα, IL1β, and IFNγ are seen in human sepsis, they are considered to be pro-inflammatory cytokines, and not sepsis-specific." (PMID 37175585, 2023). "Additionally, NaHS treatment in a rabbit model of urinary-derived sepsis showed downregulation of pro-inflammatory markers TNF and NF-kB, and upregulation of anti-inflammatory IL-10." (PMID 36978997, 2023). "This study aimed to determine the effects of MLT application in lipopolysaccharide (LPS)-induced sepsis in Wistar rats by determining the levels of liver tissue pro-inflammatory cytokines (TNF-α, IL-6) and NF-κB as well as hematological parameters indicating the state of sepsis." (PMID 38203627, 2023). "It is possible that in sepsis, TNF-α production could precede macrophage expansion, and monocytes could be induced into a pro-inflammation M1 phenotype by TNF-α stimulation." (PMID 36828453, 2023). "A positive correlation was also detected between the TNF-α rs1800629 A allele and sepsis, while a negative correlation was detected with the ACE rs1799752 insertion genotype and the severity of pneumonia." (PMID 37630611, 2023). "Another study highlighted elevated levels of TNF-α following CLP induction, indicating that sepsis is a crucial condition associated with the overproduction of inflammatory cytokines, which may lead to leukocyte recruitment and tissue damage." (PMID 38313162, 2023). "Furthermore, the levels of IL-1β and TNF-α in lung tissues from mice with sepsis were markedly decreased by LMT-28." (PMID 36643585, 2023).
Sepsis (continued). "In addition, sepsis significantly increased serum levels of lactate, TNF-α and IL-6, which were effectively decreased by melatonin administration." (PMID 37205094, 2023). "Moreover, TNF triggers an inflammatory response that culminates in the development of a wide spectrum of hyper-inflammatory diseases like arthritis, sepsis, and pneumonia." (PMID 37280310, 2023). "Indeed, others have reported surprisingly low average inflammatory cytokine concentrations, especially of the traditional sepsis cytokine TNF, in sepsis cohorts following the sepsis-3 definition." (PMID 37869001, 2023). "Elevated levels of pro-inflammatory cytokines TNF-α, IL-6 and chemokines are the markers of sepsis." (PMID 37266014, 2023). "Most importantly, 2K4L showed remarkable protection in A. baumannii-infected sepsis mice by downregulating the expression of proinflammatory signaling pathway proteins, leading to a decrease in the production of the proinflammatory factors TNF-α and IL-6." (PMID 37942076, 2023). "It revealed that apoE23 therapy effectively reduced plasma levels of TNF-α, IL-6, and LPS; decreased bacterial load in the spleen tissue homogenate; and alleviated infection-induced lung, liver, and small intestine injuries in mice with sepsis." (PMID 37533741, 2023). "Furthermore, knockout of TLR4 results in decreased mortality and expression of IL-6 and TNF-α, with better global ventricular function in a sepsis animal model." (PMID 37600769, 2023). "During sepsis, there may be an unbalanced inflammatory response due to cytokine storm, and IL-1, IL-6, and TNF-alpha may be produced in excessive amounts and may increase the production of other proinflammatory cytokines." (PMID 38275661, 2023). "Indeed, we have shown elevated TNF‐α (~3×) in patients with a diagnosis of sepsis, and this cytokine is also released (~×2) in vitro from B‐ and T‐cells stimulated with LPS/PepG." (PMID 37021779, 2023). "This article constructed a mouse model of sepsis and used purified mouse neutrophils for subsequent detection experiments and found that the expression of inflammatory cytokines TNF‐α, IL‐1β, and IL‐6 in activated neutrophils was significantly upregulated, consistent with previous research." (PMID 37647440, 2023). "Additionally, LPS caused elevated levels of TNF-α, IL-1β, IL-6, and MCP-1 in the supernatant of HK-2 cells, showing that there was increased inflammation in our cellular models of sepsis." (PMID 37085762, 2023). "Although Ezh2 impacts on sepsis are still inconclusive, Ezh2 is one of the upregulated genes in LPS-tolerant macrophages which is improved by the Ezh2 inhibitor (enhanced TNF-α expression) as an interesting control of macrophage through epigenetic manipulation." (PMID 37239864, 2023). "Finally, proinflammatory cytokines such as tumor necrosis factor alpha (TNFα) and interleukin 1 (IL-1) as well as high amounts of nitric oxide (NO) are released contributing to the organ dysfunctions in sepsis." (PMID 35563079, 2022). "This nano drug can improve the overall survival rate of sepsis caused by Gram-negative bacteria and inhibit inflammatory factor (TNF-α And IL-6) and inhibit E. coli." (PMID 36110326, 2022). "Therefore, in septic patients, LPS-stimulated TNF-α secretion by monocytes at a serum concentration below 200 ng/L can be used as a cutoff to diagnose sepsis-induced immunosuppression." (PMID 36209190, 2022). "In accordance with these findings, the present study showed that linagliptin suppressed TNF-α–induced inflammation in vitro and LPS-induced inflammation in vivo, suggesting its potential to be an adjuvant treatment for sepsis and other inflammation-related diseases." (PMID 35328486, 2022). "However, high levels of TNF due to genetic disorders or persistent infections can contribute to autoinflammatory and autoimmune diseases or life-threatening conditions like sepsis." (PMID 35166321, 2022).